PDCD4 (programmed cell death 4)
Diseases named in the same sentence as PDCD4 in open-access papers (continued):
Sharing a sentence is not in itself a finding about the gene and the disease.
tumor (continued). "Pulsatile shear stress activates several signaling pathways including the PI3K/Akt pathway; in tumor cells, phosphorylated Akt can activate the 70-kDa ribosomal protein S6 kinase (p70-S6K), which may phosphorylate PDCD4 for ubiquitin binding." (PMID 24626527, 2014). "Two of the best described miR-21 targets are the tumor suppressors PDCD4 and PTEN." (PMID 25177545, 2014). "The tumor suppressor, PDCD4, was predicted to be one such potential target." (PMID 24348845, 2014). "Thus, PDCD4 regulates molecules functioning during tumor cell proliferation, apoptosis, transformation, invasion and autophagy." (PMID 24626527, 2014). "In addition to being a suppressor of malignant transformation, tumorigenesis, and tumor progression, Pdcd4 is up-regulated in apoptosis and cellular senescence." (PMID 23469214, 2013). "Not surprisingly, miR-21 gene expression was markedly reduced (∼70%), while the expression of PTEN and PDCD4 (miR-21-target genes) was enhanced in tumor tissue from EF24-treated mice, which is similar to the effect of EF24 on miR-21 gene expression in DU145 cells in vitro." (PMID 23940701, 2013). "Moreover, c-Jun activity is essential for maintenance of the transformed phenotype, and inhibition of c-Jun activity by Pdcd4 suppresses the tumor cell phenotype." (PMID 23469214, 2013). "We proposed that there might be a concentration threshold, when exceeded, the inhibitory function of PDCD4 on tumor progression would occur." (PMID 22272332, 2012). "They confirmed for the first time an inverse correlation between miR-21 and Pdcd4 protein expression and proposed that miR-21 has a crucial role in post-transcriptional down-regulation of tumor suppressor Pdcd4, whose function is to stimulate cancer cell invasion, intravasation, and metastasis." (PMID 23091478, 2012). "Regardless of these differences, regulation of PDCD4 serves as the common mechanism underlying the anti-tumor actions of resveratrol in these cells." (PMID 23272133, 2012). "In mammals, Pdcd4 functions as a tumor suppressor, raising the possibility that this function may be conserved in flies." (PMID 22252300, 2012). "Stabilization of the β-TrCP-target Pdcd4 provides an attractive tool for the identification of novel β-TrCP-inhibitors, which might be further developed for use in anti-tumor therapies." (PMID 23056346, 2012). "miR-21-5p negatively regulates an innate immune receptor, TLR4 (toll-like receptor 4) by targeting the proinflammatory tumor suppressor, PDCD4 (programmed cell death protein 4), as well as directly modulating a key cytokine in immune regulation, IL-12 (interleukin 12)." (PMID 22937080, 2012). "PDCD4 may play a critical function in arresting cell cycle progression at key checkpoint, thus inhibiting cell proliferation, as well as suppressing tumour metastasis." (PMID 22272332, 2012). "Therefore, we set out to identify novel stabilizers of the tumor suppressor Pdcd4, which interfere specifically with β-TrCP-mediated degradation of Pdcd4." (PMID 23056346, 2012). "PDCD4 was first identified as a transformation suppressor gene in a mouse keratinocyte (JB6 cells) model of tumor promotion, in which high PDCD4 levels rendered cells resistant to transformation by the tumor-promoter 12-O-tetradecanoyl-phorbol-13-acetate (TPA)." (PMID 20831814, 2010). "In addition to the phosphoproteomics results, we provide evidence from western blot validation that the tumor suppressor, programmed cell death factor 4 (PDCD4), is a previously unidentified phosphorylation target of CXCL12 signaling in all CLL cells probed." (PMID 20661426, 2010). "Although PDCD4 is known to be a key regulator that controls tumor growth and invasion, the role of PDCD4 in NPC progression remains unclear." (PMID 20398343, 2010). "PDCD4 expression is down-regulated or lost in several tumor types." (PMID 20602797, 2010).
tumor (continued). "As a cancer-promoting gene, PLAG1 plays an essential role in the processes of adenocarcinoma formation and malignant transformation in various types of tumors, whereas PDCD4 is a tumor suppressor gene that inhibits neoplastic transformation and tumor cell invasion and facilitates apoptosis." (PMID 21192833, 2010). "In combination, these effects may reduce the growth regulating/tumor-suppressor capacity of PDCD4, thereby contributing to CLL cell survival and the malignancy phenotype." (PMID 20661426, 2010). "Furthermore the expression levels of PDCD4 appeared slightly higher in tumours than in normal tissues." (PMID 20122155, 2010). "Several recent studies have shown that the tumor suppressor PDCD4 is a target of miR-21." (PMID 21192833, 2010). "Programmed cell death 4 (PDCD4) is found to be a tumor transformation suppressor." (PMID 19480673, 2009). "Several studies have been conducted to investigate the role of Pdcd4 during tumour progression." (PMID 19728867, 2009). "Reduction in Pdcd4 expression correlated with shortened disease-free survival suggesting that it might have a potential role in tumour suppressor." (PMID 19728867, 2009). "Later studies showed that PDCD4 was a suppressor of tumor cell transformation." (PMID 19480673, 2009). "Therefore, based on our FACS analysis, the upregulation of the PDCD4 protein levels by BCAA may make it useful as an anti-tumor supplement." (PMID 41439995, 2025). "Another tumor suppressor miRNA, miR-34a, targets oncogenes including MYC and Bcl-2-Associated X Protein(Bax).In contrast, oncogenic miRNAs, such as miR-21, target tumor suppressor genes like Phosphatase and Tensin Homolog (PTEN) and Programmed Cell Death 4 (PDCD4)." (PMID 39963112, 2025). "Our principal findings demonstrate that a 100-gene signature based on PDCD4 co-expression patterns robustly predicts patient survival with a hazard ratio of 2.17 while maintaining independent prognostic value after adjusting for established clinical variables including tumor stage and grade." (PMID 41614853, 2025). "Similarly, miR-21 is well known to be upregulated in almost all types of cancers, mediating various mechanisms of cancer and contributing to tumour progression by suppressing tumour suppressor genes such as PDCD4 and PTEN, while also enhancing cell proliferation and survival." (PMID 40427172, 2025). "In addition, Pdcd4 also plays an important role in regulating tumor invasion and metastasis." (PMID 40785580, 2025). "PDCD4 functions as a tumor suppressor, but its role in RCC prognosis remains unclear." (PMID 41614853, 2025). "In addition, programmed cell death 4 (PDCD4) is a tumor suppressor that induces apoptosis." (PMID 39517115, 2024). "In addition, PDCD4 can also prevent tumorigenesis by inhibiting tumor promoter-induced neoplastic transformation, and studies indicate that PDCD4 may inhibit the translation of certain mRNAs via direct binding." (PMID 36826085, 2023). "However, the detailed mechanisms by which PDCD4 behaves as a tumor suppressor are still largely unknown." (PMID 36826085, 2023). "An inflammatory tumor microenvironment may attenuate PDCD4 protein expression." (PMID 35795053, 2022). "Upregulation of miR−503 by targeting PDCD4 could enhance tumor growth and invasion in LSCC." (PMID 35402235, 2022). "Downregulation of miR-21 by targeting PDCD4 could reduce tumor growth and invasion in SACC." (PMID 35402235, 2022). "Although the authors stated that there was a statistically significant effect on PDCD4 expression, this seems relatively minor (10%) and it is questioned whether this is significant biologically and whether suppression of tumour growth may have occurred via another tumour suppressor." (PMID 35847932, 2022).
tumor (continued). "Overall, although there is ever-increasing evidence that PDCD4 dysregulation may be integral to cellular transformation during tumorigenesis, relatively little is known about how the protein functions as a tumour suppressor and the regulation of its expression in cancers of the GI tract." (PMID 35847932, 2022). "As PDCD4 has been shown to be downregulated after stimulation with mitogens, abrogating the possible anti-proliferation and apoptosis-inducing function of the protein, it may be questioned how PDCD4 acts as a tumour suppressor." (PMID 35847932, 2022). "Moreover, little is known about PDCD4 expression in the tumor microenvironment." (PMID 33801444, 2021). "Furthermore, programmed cell death 4 (PDCD4) exerts functions as a tumor suppressor, it could suppress tumor growth and induce apoptosis of human HCC cell lines to inhibit the development of HCC." (PMID 34456908, 2021). "It is unclear though how PDCD4 contributes to Clark level, particularly as Clark level is not considered during staging, but it is possible that PDCD4 upregulation may be employed to control local tumor aggressiveness." (PMID 33801444, 2021). "In addition, NF-κB/miR-21-5p/PDCD4 signaling was involved in tumor growth and metastasis." (PMID 34249905, 2021). "Thus, downregulation of STAT3 directly or indirectly via controlling the expression of miR-21 and/or PDCD4 in SACC may eventually inhibit tumor growth and invasion." (PMID 34066762, 2021). "Furthermore, silencing of PDCD4 has been shown to affect the cellular DNA-damage response, suggesting that decreased PDCD4 expression might compromise genomic stability and contribute to tumor development." (PMID 32066800, 2020). "However, the mechanism by which PDCD4 is down-regulated and regulates tumor growth remains elusive." (PMID 33304903, 2020). "Similarly, the decreased expression of the tumor suppressor and apoptosis-inducing factor PDCD4 might play a role in the increased survival of PTPN2 KO T cells." (PMID 32726622, 2020). "Our data identify PDCD4 as a key regulator of cell cycle- and DNA-related functions that are inhibited when it is silenced, suggesting that decreased expression of PDCD4 might contribute to tumor development by compromising genomic integrity." (PMID 32066800, 2020). "However, PDCD4 gene mutations have not been found in tumor cells but gene expression was post transcriptionally downregulated by micro environmental factors such as growth factors and interleukins." (PMID 31075975, 2019). "Moreover, Linc00472 acted as a tumor suppressor by sponging miR-196a and releasing PDCD4." (PMID 29930217, 2018). "Moreover, miR-196a or si-PDCD4 weakened the anti-tumor effect of Linc00472 on CRC cells." (PMID 29930217, 2018). "Furthermore, PDCD4 knockdown abolished the tumor suppressive effects of Linc00472 in CRC cells." (PMID 29930217, 2018). "Moreover, PDCD4 expression was positively correlated with TUG1 expression in ESCC tumor specimens." (PMID 30519392, 2018). "Experiments that solidify the importance of interaction between PRMT5 and PDCD4 revealed that when either protein is mutated, the tumor promoting activity of the pair is lost, indicating that PRMT5-mediated PDCD4 methylation is crucial for enhanced tumor growth." (PMID 30613353, 2018). "In mouse epidermal JB6 cells, which are resistant to anchorage-dependent cell death and neoplastic transformation, high levels of PDCD4 expression could be induced in response to the presence of tumor promoters such as 12-O-tetradecanoylphorbol-13-acetate and tumor necrosis factor-alpha." (PMID 27852288, 2016). "Therefore, it has been suggested that PDCD4 is a potent tumor suppressor gene." (PMID 27852288, 2016). "Interestingly, in contrast to most tumor suppressors, Pdcd4 appears not to be inactivated mutationally." (PMID 26982744, 2016). "Additionally, PDCD4 overexpression attenuated the promotive effect of miR-93 on tumor growth, suggesting that miR-93 might promote tumor growth by silencing PDCD4." (PMID 27021515, 2016).
tumor (continued). "Additionally, PDCD4 overexpression attenuated the promotive effect of miR-208a-3p on tumor growth, suggesting that miR-208a-3p might promote tumor growth by silencing PDCD4." (PMID 27634902, 2016). "Thus, PDCD4 could regulate critical events such as proliferation, differentiation, apoptosis and invasion in tumor progression." (PMID 26703592, 2015). "In addition, PDCD4 can translocate between the nucleus and cytoplasm, and this kind of intracellular translocation may play an important role for tumor development." (PMID 26703592, 2015). "PDCD4 could inhibit invasion-related urokinase plasminogen activator receptor expression, invasion or infiltration of blood vessels, and metastasis; therefore, decreased expression of PDCD4 plays an important role in tumor occurrence, development and prognosis." (PMID 25144746, 2014). "However, PDCD4 depletion significantly ameliorated BB-induced growth inhibition, indicating that PDCD4 could be a downstream effector protein in the BB-induced cell growth inhibition pathway, and that it might be a tumor suppressor in MM cells." (PMID 25000828, 2014). "On the whole, PDCD4 functions as tumor suppressor in the nucleus in normal cells, however, when cells were under certain environmental stress or undergoing potential transformation from normal to malignant, one of the cellular response might be transporting PDCD4 to the cytoplasm." (PMID 22272332, 2012). "Several mechanisms could account for the anti-tumor response of PDCD4." (PMID 23272133, 2012). "However, once the disease recurred, the protective effect of Pdcd4 might be limited and other molecular events could have overtaken, and the tumour somehow becomes more resistant to the treatment, such as second line chemotherapy." (PMID 19728867, 2009). "Downregulation of PTEN reduces apoptosis and enhances angiogenesis through the HIF-1α signaling pathway, while suppression of PDCD4 and SPRY1 further facilitates tumor cell proliferation, migration, and invasion." (PMID 41511367, 2026). "Mechanistically, miR-21 is postulated to promote tumor progression by inhibiting tumor suppressor genes, such as TPM1 and PDCD4, which play a crucial role in controlling invasion and inducing cell death through apoptosis." (PMID 41511367, 2026). "Functionally, miR-21 promotes tumorigenesis by suppressing multiple tumor suppressor genes that usually restrain proliferation, invasion, and survival, including PTEN, PDCD4, and SPRY1." (PMID 41511367, 2026). "Furthermore, the activated FOXOs, as well-established regulators of apoptosis, may lead to cell death through the activation of downstream targets such as PDCD4, a tumor suppressor protein known to facilitate programmed cell death and suppress tumor progression." (PMID 41462911, 2025). "Acts as an oncomiR by inhibiting tumor‐suppressor genes such as PTEN and PDCD4, activating the PI3K/AKT pathway for cell survival and proliferation." (PMID 40959208, 2025). "Among the most consistently upregulated molecules, miR-21 functions as a central oncogenic driver by targeting tumor suppressors such as PTEN and PDCD4, leading to activation of the PI3K/AKT and MAPK pathways that promote cell survival and chemoresistance." (PMID 41226828, 2025). "Downstream mmu-miR-21a-5p mRNA targets, Pten, and programmed cell death protein 4 (Pdcd4) were analyzed using RT-qPCR analysis in mice treated with AAV8 on day 3 and day 6 post tumor implantations." (PMID 39563028, 2025). "MiR-21 is an oncomiR whose overexpression promotes cancer progression by suppressing tumour-suppressor genes such as PTEN, PDCD4, and RECK, leading to increased proliferation, invasiveness, and resistance to apoptosis." (PMID 41375254, 2025).
tumor (continued). "For instance, miR-21, which is upregulated in breast, lung, gastric, and brain cancers, inhibits tumor suppressors like PTEN, PDCD4, and TPM1, thereby enhancing tumor growth, metastasis, and chemoresistance." (PMID 40259326, 2025). "For instance, exosomal miR-21 can downregulate PDCD4, TPM1, and PTEN in neighboring cells, promoting tumor invasion and immune evasion." (PMID 41226828, 2025). "Computational prediction identified several tumor-suppressor genes, including PTEN, STAT3, RhoB, and PDCD4, as potential direct targets of miR-21-5p." (PMID 41465544, 2025). "miR-21, a highly upregulated oncomiR, promotes tumour growth and drug resistance by suppressing genes such as phosphatase tensin homolog (PTEN) and programmed cell death 4 (PDCD4)." (PMID 41375254, 2025). "We found that the tumor suppressor genes Pten and Pdcd4 were significantly upregulated by 7.9-fold and 6.6-fold, respectively, in mice treated with AAV8-CRISPR in mCherryPOS tumor cells compared to AAV8-control." (PMID 39563028, 2025). "miRNAs like miR‐21 function as oncogenes by suppressing tumor‐suppressor genes such as PTEN and PDCD4, thereby activating pathways that promote cell proliferation and survival." (PMID 40959208, 2025). "miR-21 facilitates tumor growth, survival, and invasion by targeting a range of tumor suppressor genes, including PTEN, PDCD4, and PTPN14." (PMID 41008657, 2025). "For example, miR-21 has been reported to downregulate PTEN, PDCD4, and RECK—tumor suppressors that are essential for maintaining cellular homeostasis—thereby potentially promoting abnormal cell proliferation and migration in non-target tissues." (PMID 41437101, 2025). "For example, anti-miR-21 (often in LNA-modified form) has been used in various cancer cell models to restore tumor suppressor expression (such as PTEN and PDCD4) and reduce cellular motility and invasiveness." (PMID 41226828, 2025). "Elevated miR-21-5p levels are known to repress tumor suppressors such as PTEN and PDCD4, thereby promoting proliferation, invasion, and survival." (PMID 41153743, 2025). "This resulted in upregulation of ER-alpha, the tumor progression protein GRP78 (78-kDa glucose-regulated protein) and downregulation of the tumor suppressor protein PDCD4 (programmed cell death protein 4)." (PMID 39890941, 2025). "One of the most studied oncomiRs, miR‐21 targets and suppresses the expression of tumor‐suppressor genes such as PTEN and PDCD4 that activate the PI3K/AKT pathway promoting cell survival, proliferation, and growth." (PMID 40959208, 2025). "For example, in cancer, miRNAs often act as either oncogenes (oncomiRs) or tumor suppressors; e.g., miR-21 is an oncomiR frequently upregulated in cancers, promoting tumor growth and metastasis by targeting tumor suppressor genes such as PTEN and PDCD4." (PMID 40149481, 2025). "It promotes tumor growth and survival primarily through suppression of PTEN, resulting in PI3K/AKT pathway activation, and by targeting PDCD4, which enhances AP-1-mediated transcription of genes driving proliferation and invasion." (PMID 40940980, 2025). "By targeting several proteins such as Tap 63, Heterogeneous Nuclear Ribonucleoprotein K (HNRPK), and Programmed Cell Death Protein 4 (PDCD4), miR-21 achieved inhibition of apoptotic pathways, hence further contributing to tumor cell proliferation." (PMID 39055532, 2024). "MiR-21, a prototypical oncogenic miRNA, reigns supreme in glioblastoma, promoting tumor growth and therapy resistance by targeting tumor suppressors such as PTEN and PDCD4." (PMID 38920691, 2024). "Recently programmed cell death protein 4 (PDCD4) is considered to be involved in the progression of diabetic cardiomyocytes, which serves as a tumor suppressor in prior studies." (PMID 38390204, 2024).